RB1 (RB transcriptional corepressor 1)
Diseases named in the same sentence as RB1 in open-access papers (continued):
Sharing a sentence is not in itself a finding about the gene and the disease.
retinoblastoma (continued). "This study aims to perform a mutational analysis of the RB1 gene using Next Generation Sequencing to investigate RB1 gene mutations in Jordanian patients with unilateral Retinoblastoma." (PMID 39234041, 2024). "Children with germline mutations in RB1 have an increased risk of developing retinoblastoma and other cancers later in life." (PMID 38473926, 2024). "In spite of RB1-proficiency, the increased levels of E2f cause a cancer phenotype that resembles that of a RB1-deficient retinoblastoma." (PMID 37606819, 2024). "Human cone precursor maturation’s unique cell-signaling circuitry makes them sensitive to RB1 loss, leading to proliferation and lesion formation resembling retinoma and retinoblastoma." (PMID 38398694, 2024). "GWAS have shown unique genetic variations surrounding the RB1 gene in retinoblastoma, underlining its essential involvement in the illness and providing putative modifier genes affecting disease severity in hereditary instances." (PMID 38540335, 2024). "Retinoblastoma (RB) is the most common type of intraocular malignancy in infancy and childhood, usually caused by a mutation in the retinoblastoma 1 (RB1) gene on chromosome 13, which occurs in one or both eyes." (PMID 39620227, 2024). "Patients with familial retinoblastoma are heterozygous for a Rb1 mutation with subsequent loss of the remaining allele producing the pediatric eye tumor retinoblastoma." (PMID 38248470, 2024). "Retinoblastoma (RB) is a rare, primary malignant tumour which occurs in the embryonic retina due to mutations in the RB1 gene." (PMID 39020265, 2024). "Constitutively active E2Fs during the cell cycle as a result of RB1 inactivating mutations is a major driving force in retinoblastoma carcinogenesis." (PMID 37606819, 2024). "Heritable retinoblastoma is characterized by a mutation in one RB1 gene allele across all body cells." (PMID 38792122, 2024). "Nearly all retinoblastomas develop after both RB1 alleles are deactivated in a cone cell precursor during retinal development." (PMID 39000021, 2024). "While RBL1 and RBL2 are infrequently mutated in human cancers, RB1 mutations are prevalent across various cancer types, such as retinoblastoma, osteosarcoma, pinealoma, and melanoma." (PMID 38672640, 2024). "While RB1 loss signifies the potential for a susceptible retinal cell to turn malignant, it typically results in retinoma, a benign precursor to retinoblastoma." (PMID 39735524, 2024). "Analysis of tumour DNA is the gold standard for the identification of RB1 somatic variation in retinoblastoma, with diagnostic yield > 95%." (PMID 38672657, 2024). "Inhibitory hyperphosphorylation of the retinoblastoma protein (Rb) in RB1-proficient retinoblastomas has been proposed to explain the RB1-deficient-like phenotype of RB1-proficient retinoblastomas." (PMID 37606819, 2024). "Most studies on retinoblastoma have focused on RB1 mutations that result in the deactivation of its alleles." (PMID 38540335, 2024). "The major gene responsible for retinoblastoma is RB1, and it harbors a large spectrum of pathogenic variants." (PMID 37658463, 2023). "Inactivation of RB1 by inherited or somatic mutation occurs in retinoblastoma and various other types of tumors." (PMID 37917619, 2023). "Hereditary retinoblastoma patients are more likely to develop osteosarcoma, with RB1 mutations detected in 30–75% of these tumors." (PMID 38201628, 2023). "RB1 gene mutations not only predispose individuals to retinoblastoma but also increase the risk for secondary tumors like soft tissue sarcomas, melanoma, brain tumors, and some carcinomas, including those of the lung, breast, and bladder." (PMID 38201628, 2023). "Three cases of retinoblastoma harbored unique RPA1 variants (2 ultra-rare) with 2 cases having concomitant germline RB1 mutation." (PMID 37869077, 2023). "RB1 mutation is a rate-limiting step for development of sporadic and inherited retinoblastoma but also occurs in other types of tumors." (PMID 37917619, 2023).
retinoblastoma (continued). "This means that in order for retinoblastoma to develop, one copy of mutated RB1 gene needs to be inherited from one parent while the other copy, inherited from the other parent, has to be struck by mutation in retinal cells." (PMID 37658463, 2023). "Retinoblastoma in humans is the result of deficiency of RB1, and individuals who inherit one defective copy of RB1 frequently develop retinoblastoma early in life." (PMID 37712424, 2023). "In sporadic forms, both mutations occur in somatic cells; in heritable retinoblastoma, the first RB1 mutation is inherited and only the second mutation occurs as a somatic event." (PMID 36910590, 2023). "Unlike children bearing germline RB1 mutations, heterozygous Rb1 mutant mice fail to develop retinoblastoma." (PMID 37712424, 2023). "Retinoblastoma is a common childhood intraocular malignancy, the bilateral form of which most commonly results from a de novo germline pathogenic variant in the RB1 gene." (PMID 35361938, 2023). "Retinoblastoma has an autosomal dominance pattern with each offspring having a 50% risk of inheriting the RB1 gene mutation that has a 90% penetrance." (PMID 37667345, 2023). "RB-1 deficient iPSCs were differentiated into the retina, to gain insight into the cell of origin for retinoblastoma and cellular events in retinoblastoma tumorigenesis." (PMID 37456734, 2023). "The RB1 gene mutation in retinoblastoma disrupts the normal functioning of the retinal cells, including both photoreceptor cells (rods and cones) and neuronal cells." (PMID 37777551, 2023). "As all germline de novo cases present bilaterally, any factor which encourages the development of a de novo germline pathogenic variant in RB1 should create a higher level of bilateral retinoblastoma within a population." (PMID 35361938, 2023). "It was later discovered that the related protein RBL1 (also known as p107) protects against tumorigenesis in mice and mutation in both Rb1 and Rbl1 is needed for retinoblastoma development in mice." (PMID 37712424, 2023). "The resulting loss of function of the RB1 locus, following genetic mutation or deletion, leads to the activation of E2F family proteins, uncontrolled cell proliferation, and initiation of retinoblastoma." (PMID 37509256, 2023). "In case of bilateral retinoblastoma, the RB1 gene, in most of the patients, acquires a de novo mutation during spermatogenesis, indicating that it is mostly the paternal chromosome that is vulnerable to mutations." (PMID 37667345, 2023). "We identified 256 primary tumours from 10 cancer types in the TCGA that had potentially deleterious mutations in the Retinoblastoma-encoding RB1 gene in at least 10 samples per cancer type." (PMID 37883365, 2023). "The missense variant identified in RB1 was previously classified in ClinVar as pathogenic/likely pathogenic (P/LP; variation ID 428682), identified in patients with hereditary retinoblastoma." (PMID 37445641, 2023). "Retinoblastoma (RB) is the most common ocular neoplasm in children, whose development depends on two mutational events that occur in both alleles of the retinoblastoma susceptibility gene (RB1)." (PMID 38001596, 2023). "Several studies in rodent models showed cooperation between MYCN and loss of RB1 in accelerating retinoblastoma formation." (PMID 36982482, 2023). "RB1 is the most recurrently mutated gene in intraocular retinoblastoma and there are at least 51 described types of RB1 somatic mutations in this disease." (PMID 36148636, 2023). "Retinoblastoma is typically caused by the RB1 tumor suppressor gene becoming inactive on both alleles." (PMID 37777551, 2023). "Retinoblastoma results from either a somatic or a germline pathogenic variant in the RB1 tumour suppressor gene, causing inactivation." (PMID 35361938, 2023).
retinoblastoma (continued). "Alterations in the expression and sequence of the RB1 gene have been implicated in several cancers besides retinoblastoma where they were originally characterized (reviewed in 391)." (PMID 38577257, 2023). "The RB1 is encoded by the RB1 gene which was discovered in the malignant tumor of the retina known as the retinoblastoma." (PMID 37506143, 2023). "Careful follow-up of children with unilateral retinoblastoma, including screening for germline RB1 mutation, is of utmost importance." (PMID 35839812, 2022). "Sporadic retinoblastoma, on the other hand, is associated with somatic genetic inactivation of both RB1 alleles with the lower probability of two genetic hits accounting for the delayed age at diagnosis for these cases." (PMID 35368709, 2022). "Further analyses are needed to clarify the genetic landscape in this age group; of note, even the sporadic retinoblastoma patient presented a RB1 germline mutation." (PMID 35565372, 2022). "The majority of heritable retinoblastoma patients have a de novo RB1 variant, as only 10% inherit the variant from a parent (autosomal dominant transmission)." (PMID 35340648, 2022). "Timely diagnosis and prompt management of Retinoblastoma (Rb), the most common primary intraocular malignancy in children linked to mutations in the RB1 gene, are critical for the cure." (PMID 36713556, 2022). "These patients inherit one mutationally inactivated RB1 allele and have increased risk for additional cancers unrelated to retinoblastoma later in life." (PMID 35368709, 2022). "Upon the occurrence of a somatic mutation (the second “blow”) on the other RB1 allele, they will develop retinoblastoma." (PMID 35626065, 2022). "Retinoblastoma (Rb) is a type of malignant tumor due to abnormal retinogenesis with biallelic mutations of the RB1 gene." (PMID 36714839, 2022). "Among them, the mutation of RB1 gene is the prime cause for the pathogenesis of hereditary and sporadic retinoblastoma." (PMID 35359459, 2022). "Retinoblastoma is a rare, intraocular paediatric cancer that originates in the neural retina and is most frequently caused by bi-allelic loss of RB1 gene function." (PMID 35729105, 2022). "Ablation of Rb1/Rbl2 leads to rapid development of multifocal retinoblastoma while ablation of Rb1/Rbl1 causes more delayed development of unifocal retinoblastoma." (PMID 35368709, 2022). "Subseqeunt studies supported the notion that ARR3-positive maturing cone photoreceptor cells are especially sensitive to loss of RB1 expression, reacting with re-entry into cell cycle and development of retinoblastoma." (PMID 35565295, 2022). "The molecular, cellular, and genetic characteristics of the patient-derived retinal organoids recapitulated human retinoblastomas, which sheds light on the molecular causes of RB as well as the RB1 gene inactivation mechanism." (PMID 36359825, 2022). "Patients with heritable retinoblastoma (45%) demonstrate biallelic loss of the RB1 gene, and in most patients, bilateral retinoblastoma develops." (PMID 36245757, 2022). "Thirty-one patients (27.4%) were treated at least once with neoadjuvant intra-arterial chemotherapy, while four patients had RB1 germline mutations and had previously been treated for retinoblastoma." (PMID 36176408, 2022). "Three of four patients with retinoblastoma had positive family cancer history and a confirmed germline RB1 mutation." (PMID 35200584, 2022). "In non‐heritable retinoblastoma, both RB1 variants arise in the developing retina, whereas in heritable retinoblastoma, a germline RB1 variant is present." (PMID 35340648, 2022). "According to the Retinoblastoma Gene Mutation Database (RBGMdb), a total of 3393 variants of RB1 have been reported so far." (PMID 36175480, 2022). "The main cause of retinoblastoma is biallelic inactivation of RB1, which can occur as part of a heritable tumor predisposition disease." (PMID 35565295, 2022).
retinoblastoma (continued). "Retinoblastoma is a tumor of the eye in children under the age of five caused by biallelic inactivation of the RB1 tumor suppressor gene in maturing retinal cells." (PMID 35565295, 2022). "The number and type of somatic copy number alterations spontaneously acquired during retinoblastoma development suggest Rb1/Rbl2 deficient murine retinoblastomas are more like their human counterparts." (PMID 35368709, 2022). "Loss or inactivation of RB1, as observed in retinoblastoma, leads to the sustained activation of E2F family proteins resulting in uncontrolled cell proliferation." (PMID 36338723, 2022). "Children with bilateral disease have a pathogenic germline RB1 variant (hence heritable retinoblastoma), but some children with heritable retinoblastoma only develop unilateral disease, due to variation in penetrance and expressivity." (PMID 35340648, 2022). "One notable example is that of Retinoblastoma protein (RB1): Multiple frameshift and stop-gained variants of RB1 with two such altered linkers/spacers are implicated in a very rare retinoblastoma condition." (PMID 35275927, 2022). "In conclusion, we demonstrate Hexokinase 1 (HK1) to be significantly reduced in Rb tumors and RB1 null retinoblastoma cells, wherein their loss mediates a critical metabolic adaptation towards enhanced mitochondrial respiration." (PMID 36291051, 2022). "UHRF1 is overexpressed in different cancers that frequently present RB1 mutations, including lung, breast, bladder, colorectal cancer, and retinoblastoma." (PMID 36068209, 2022). "In fact, aberrant splicing of the RB1 gene was found to be the dominant cause of retinoblastomas in a recent study." (PMID 36497448, 2022). "MYCNA gene copy-number mutations causing over-expression is one of the most frequent mutations found in retinoblastoma after RB1 loss-of-function." (PMID 35729105, 2022). "DNA analysis revealed 27 different causative RB1 mutations in 30 patients (26.3%), which were identified in 4/59 (6.8%) patients with unilateral Rb and 26/55 (47.3%) patients with bilateral Rb (p < 0.0001)." (PMID 35960463, 2022). "As another example, human retinoblastoma development was modeled using iPSCs from 15 people with germline RB1 mutations." (PMID 36359825, 2022). "Retinoblastoma is caused by sporadic somatic mutations in the RB1 gene, but about one-third of cases arise in infants with germline mutations." (PMID 35269741, 2022). "EZH2 inhibitor has been reported to be efficient efficacy in RB1-mutational Y79 and Weri retinoblastoma cells." (PMID 36175480, 2022). "The retinoblastoma tumor suppressor family contains the proteins, pRb, p107, and p130, encoded by the RB1, RBL1, and RBL2 genes, respectively." (PMID 35250950, 2022). "The consensus panel also recommended genetic counseling and testing for mutation of RB1 in all patients with personal or family history of retinoblastoma." (PMID 36553382, 2022). "Inherited mutations in RB1 were initially identified to predispose for retinoblastoma and osteosarcoma." (PMID 35361964, 2022). "Mutation of the RB1 tumor suppressor gene is fundamental in retinoblastoma initiation and progression although its downstream mechanism has not been well elucidated." (PMID 36230849, 2022). "Retinoblastoma (Rb), the most frequent malignant intraocular tumor in childhood, is caused by mutations in the retinoblastoma gene (RB1) situated on chromosome 13q14.2." (PMID 36408154, 2022). "RB transcriptional corepressor 1 (RB1) is the first tumor suppressor gene mutated in retinoblastoma." (PMID 35299734, 2022). "So far, BCOR is the only gene recurrently mutated in retinoblastoma, found in about 10% of cases, leaving inactivation of RB1 as the main driver of tumor formation." (PMID 35565295, 2022).
retinoblastoma (continued). "The proband was referred for molecular diagnostic investigation of the RB1 gene, having presented at 8 months old with bilateral retinoblastoma; at age 12 years he also developed an osteosarcoma of the right tibia." (PMID 35014072, 2022). "Retinoblastoma (Rb) is the most common pediatric ocular malignancy which is caused by mutations in the RB1 gene." (PMID 36291051, 2022). "It was established very early that the homozygous deletion of Rb1 is the major genetic alteration driving the development of childhood retinoblastoma due to loss of Rb1 function as a cell cycle regulator." (PMID 35267571, 2022). "Retinoblastoma, the most frequent malignant intraocular tumor in childhood, is caused by mutations in the retinoblastoma gene (RB1)." (PMID 36408154, 2022). "The mechanism of actions for CDK4/6 inhibitors is centered on RB1, the product of the retinoblastoma tumor susceptibility gene RB1." (PMID 35740538, 2022). "Retinoblastoma originates mostly in association with a mutation in the RB1 gene, a tumor suppression gene." (PMID 35288594, 2022). "For instance, regarding retinoblastoma, Liu and colleagues genomically edited human embryonic stem cells (hESCs) with either homozygous RB1 loss-of-function mutation or deletion, and then differentiated these mutant cells into retinoblastoma organoids." (PMID 36077628, 2022). "Apart from RB1 gene mutations, only a few recurrent genetic alterations have been linked to retinoblastoma development." (PMID 36497295, 2022). "This suggests that retinoblastoma carcinogenesis can progress in a functionally normal RB1 genetic background and that other oncogenic mutations, such as MYCNA, drives tumorigenic growth." (PMID 35729105, 2022). "Retinoblastoma (Rb) is pediatric eye cancer, predisposed primarily by mutations in RB1 developing cone cells of the retina." (PMID 36432697, 2022). "Retinoblastoma carcinogenesis is strongly associated with RB1 mutations and develops with high frequency after bi-allelic loss-of-function of the RB1 gene (RB1−/−)." (PMID 35729105, 2022). "In total, 36 of 47 retinoblastomas indicated RB1–/– status, 12 of which were caused by loss of heterozygosity of a nonsynonymous or high-impact germline variant." (PMID 36245757, 2022). "The hereditary retinoblastoma phenotype is thought to depend on the functional type of the underlying RB1 mutation." (PMID 34680218, 2021). "Early theories of retinoblastoma development established that loss-of-function mutations in both alleles of the RB1 gene were required to enable its development." (PMID 33670346, 2021). "Here, the authors demonstrate the first patient derived model of retinoblastoma using iPSCs from patients with germline mutations in RB1." (PMID 34315877, 2021). "To produce a laboratory model of human retinoblastoma, we created iPSCs from 15 participants with germline RB1 mutations or deletion." (PMID 34315877, 2021). "Although the response of retinal cells to the early loss of RB1 is clearly understood, retinoblastoma cells of origin remain debatable." (PMID 34815392, 2021). "Hypomorphic variants in RB1, the causative gene of retinoblastoma have been found to confer significantly lower penetrance (< 25%) as compared to more common loss-of-function variants which are highly penetrant (> 95%) for the disease." (PMID 34861889, 2021). "Retinoblastoma is a childhood eye cancer, mainly caused by mutations in the RB1 gene, which can be somatic or constitutional." (PMID 33805427, 2021). "In this work, molecular genetic assessment of DNA samples from peripheral blood lymphocytes of 332 unrelated retinoblastoma patients resulted in identification of causative RB1 gene mutations in 191 (58%) of them." (PMID 34680218, 2021). "To develop a laboratory model of human retinoblastoma formation, we make induced pluripotent stem cells (iPSCs) from 15 participants with germline RB1 mutations." (PMID 34315877, 2021).